SERPINA3 (serpin family A member 3)
Diseases named in the same sentence as SERPINA3 in open-access papers (continued):
Sharing a sentence is not in itself a finding about the gene and the disease.
keloid (2 papers, 2020 to 2023). An irregularly shaped, elevated mark on the skin caused by deposits of excessive amounts of collagen during wound healing. "Immunohistochemical analysis of the six samples showed that all of the keloids had greater protein expression of both SERPINA3 and LAMC2 in the blood vessels than the normal skin samples." (PMID 32850798, 2020). "Similarly, inhibiting SERPINA3 in well-established keloids may promote immune responses and the degradation of the ECM, thereby reducing the keloid mass and/or preventing its further outgrowth." (PMID 32850798, 2020). "Thus, given its roles in inflammation, SERPINA3 may also act in keloid pathogenesis by altering local immune responses." (PMID 32850798, 2020). "SERPINA3 and LAMC2 were the most upregulated genes in keloid VECs, and they contribute to fibrosis and inflammation in keloids." (PMID 37587491, 2023). "In the present study, we identified the genes that are up- or down-regulated in KVECs and then focused on SERPINA3 and LAMC2, both of which are sharply up-regulated in KVECs and thus may contribute to keloid pathogenesis." (PMID 32850798, 2020). "Our data suggest that SERPINA3 and LAMC2 upregulation in KVECs may contribute to the development of fibrosis and prolonged inflammation in keloid." (PMID 32850798, 2020).
keratoconus (2 papers, 2025 to 2026). A degenerative, structural disorder of the eye, characterized by a cone-shaped protrusion of the cornea. "SerpinA3, which has been demonstrated to exhibit anti-inflammatory, anti-angiogenic, antioxidant, and anti-fibrotic activities, was upregulated in the keratoconus group, perhaps as a response to the proinflammatory environment." (PMID 41601845, 2026).
metabolic syndrome (2 papers, 2023 to 2025). A cluster of metabolic risk factors for CARDIOVASCULAR DISEASES and TYPE 2 DIABETES MELLITUS. "In summary, SERPINA3/Serpina3c, a serine (or cysteine) peptidase inhibitor, has demonstrated multifaceted regulatory roles in non-neoplastic diseases, including neurodegenerative disorders, cardiovascular diseases, inflammatory conditions, and metabolic syndrome." (PMID 40076571, 2025).
multiple system atrophy (2 papers, 2013 to 2022). Multiple system atrophy (MSA) is a neurodegenerative disorder characterized by autonomic failure (cardiovascular and/or urinary), parkinsonism, cerebellar impairment and corticospinal signs with a median survival of 6-9 years. "Interestingly, SERPINA3 polymorphisms are associated with an increased susceptibility to neurological illnesses and may be related to early onset of PD and Multiple System Atrophy (MSA)." (PMID 35416570, 2022).
myocardial ischemia (2 papers, 2023 to 2025). A disorder of cardiac function caused by insufficient blood flow to the muscle tissue of the heart. "A study showed that intravenous injection of recombinant human SerpinA3 before myocardial ischemia-reperfusion could reduce myocardial injury caused by myocardial ischemia-reperfusion in mice." (PMID 37288300, 2023). "Its subtype, SERPINA3, mitigates myocardial ischemia-reperfusion injury via lactylation modification, yet promotes atherosclerotic plaque progression through NF-κB pathway activation." (PMID 41287052, 2025).
pancreatic cancer (2 papers, 2017 to 2020). "However, several other known acute-phase reactants were found not to be elevated (e.g., AHSG, SERPINA3, ITIH4, FN, F2, F8, SAP, and CD163), arguing that there may be some specificity in the inflammatory response to pancreatic cancer." (PMID 29232830, 2017).
peripheral vascular disease (2 papers, 2023 to 2025). Any disorder affecting blood flow through the veins or arteries outside of the heart. "We found that APOE, IGF1R, HMGCR, APOA1, ENG, SERPINA3 and LCN2 were hub proteins in the network, which were also predicted to be associated with peripheral vascular disease." (PMID 37496672, 2023).
psychosis (2 papers, 2020 to 2021). "Given the positive correlation between miR-223 and inflammation-associated astrocyte-enriched SERPINA3, which was also shown to be increased in both SCZ and BD patients with psychosis, it is possible that inflammation and glial activation could contribute to the expression of miR-223 in the OFC." (PMID 31775160, 2020). "Our results showed that BD patients with psychosis but not BD patients without psychosis displayed significant increases in SERPINA3, and reductions in GRIN2B, GRIA2, and ADAR2 mRNAs, similar to those seen in SCZ." (PMID 31775160, 2020).
squamous cell carcinoma (2 papers, 2012 to 2024). A carcinoma arising from squamous epithelial cells. "Moreover, a significant increase in squamous cell carcinoma proteins marker genes such as SerpinA1, SerpinA3 and EphB2 under the influence of UV radiation was observed in cells with efficiently functioning NLRP1 and NLRP3." (PMID 39839625, 2024).
ulcerative colitis (2 papers, 2021 to 2023). An inflammatory bowel disease involving the mucosal surface of the large intestine and rectum. "The fact is that inflammation is strongly associated with both ulcerative colitis and carcinogenesis, so it is necessary to conduct further research on whether the SERPINA3 protein is specifically associated with CRC or only with the inflammatory pathway as an acute-phase protein." (PMID 36672665, 2023). "Patients with ulcerative colitis (UC) have elevated expression of SERPINA3 mRNA and its protein in diseased tissues." (PMID 36672665, 2023).
acute lung injury (1 paper, 2025). A condition of lung damage that is characterized by bilateral pulmonary infiltrates (pulmonary edema) rich in neutrophils, and in the absence of clinical heart failure. "Additionally, pyridoxal phosphate, the active form of vitamin B6, has been shown in studies to be a potential candidate drug targeting the SERPINA3 gene in LPS-induced ALI (acute lung injury)." (PMID 40278587, 2025).
alcohol addiction (1 paper, 2023). "However, four genes, SERPINA3, SLC14A1, RPS6 and RPS3A, were obtained among the alcohol addiction-related differential genes." (PMID 37065902, 2023).
alcohol dependence (1 paper, 2021). Physical and psychological dependence on alcohol. "Further research is needed to elucidate the exact mechanisms by which SERPINA3 levels are associated with alcohol dependence." (PMID 35095596, 2021). "In the present study, we identified a single upregulated DEG, SERPINA3, and one hub gene among the three microarray datasets associated with alcohol dependence." (PMID 35095596, 2021). "The levels of SERPINA3 were higher in patients with alcohol dependence, which is related to the NF-κB pathway." (PMID 35095596, 2021). "According to the median value of SERPINA3 expression level in alcohol dependence group, patients were divided into high SERPINA3 (≥2677.33 pg/ml, n = 29) and low SERPINA3 groups (<2677.33 pg/ml, n = 29)." (PMID 35095596, 2021). "ELISA analysis indicated that SERPINA3 and IL-6 concentrations were significantly elevated in patients with alcohol dependence than in healthy controls (P < 0.001)." (PMID 35095596, 2021). "SERPINA3 concentrations were significantly elevated in the alcohol dependence group than in healthy controls (P < 0.001)." (PMID 35095596, 2021). "We recruited 58 individuals with alcohol dependence and 20 healthy controls to validate the hypothesis that SERPINA3 and IL-6 were dysregulated in individuals with alcohol dependence." (PMID 35095596, 2021). "In conclusion, we identified that SERPINA3 is correlated with alcohol dependence." (PMID 35095596, 2021). "The median SERPINA3 concentration in patients with alcohol dependence (n = 58) was 2677.33 pg/ml." (PMID 35095596, 2021). "We are the first to demonstrate that plasma SERPINA3 is correlated with alcohol dependence." (PMID 35095596, 2021). "This suggests that SERPINA3 is involved in inflammation during alcohol dependence." (PMID 35095596, 2021). "During alcohol dependence, activated neutrophils could be partially responsible for the elevated levels of SERPINA3 observed in our study." (PMID 35095596, 2021). "Serine proteinase inhibitor A3 (SERPINA3) plays crucial roles in multiple human diseases; however, its role in alcohol dependence clinical practice has not been confirmed." (PMID 35095596, 2021). "However, SERPINA3 may not be a potential predictive marker of relapse with patients in alcohol dependence." (PMID 35095596, 2021).
allergic asthma (1 paper, 2023). A asthma with a basis in a pathological type I hypersensitivity reaction. "The most widely reported antiprotease marker candidates for allergic asthma are SERPINB10, SERPINE1, and SERPINA3." (PMID 37987478, 2023).
anterior uveitis (1 paper, 2025). Inflammation of the iris and anterior chamber of the eye. "SERPINA3 has also been reported in association with multiple ocular diseases, including anterior uveitis and Graves’ orbitopathy." (PMID 40650225, 2025).
arterial diseases (1 paper, 2023). "Overall, the studies on Serpina3c and SerpinA3 indicate that they may play protective roles against arterial diseases, and have significant implications for understanding the pathogenesis and treatment of arterial diseases." (PMID 37288300, 2023).
autoimmune myocarditis (1 paper, 2021). Autoimmune myocarditis is an autoimmune disease that affects the heart. "Previous in vivo studies found that SERPINA3 was markedly upregulated in the mice model of experimental autoimmune myocarditis and chronic pulmonary injuries." (PMID 34943607, 2021).
bladder pain syndrome (1 paper, 2023). "Serpina3n/Serpina3 has been identified to be implicated in inflammatory diseases, but its role in interstitial cystitis/bladder pain syndrome (IC/BPS) remains unknown." (PMID 37594700, 2023).
Brain atrophy (1 paper, 2023). Partial or complete wasting (loss) of brain tissue that was once present. "We hypothesized that serum‐derived EVs from r‐DMV participants promote brain atrophy by regulating inflammation‐related proteins, particularly by downregulating C3 and upregulating SERPINA3." (PMID 37438638, 2023).
brain glioma (1 paper, 2026). A malignant glioma that involves the brain. "To explore SERPINA3 expression in human brain glioma tissues, we conducted immunohistochemistry staining to evaluate the levels of SERPINA3 protein from collected specimens." (PMID 41550507, 2026).
cerebral edema (1 paper, 2024). "Our study aimed to explore the predictive value of postoperative serum SERPINA3 levels in identifying the risk of cerebral edema and its prognostic implications in TBI." (PMID 38928660, 2024).
cerebrovascular disease (1 paper, 2024). "The role of SERPINA3 in cerebrovascular disease remains controversial." (PMID 37721405, 2024).
colitis (1 paper, 2021). Inflammation of the colon. "SERPINA3 gene expression was markedly increased in UC patient samples, colitis models and in-vitro models and showed an association with other inflammatory factors." (PMID 34943607, 2021). "The SERPINA3 mRNA level was markedly increased in the mouse colitis model and human intestinal epithelial cell inflammatory model." (PMID 34943607, 2021). "Finally, colitis model mice and an in-vitro model were established to validate the function of the SERPINA3 gene." (PMID 34943607, 2021).
desmoid tumor (1 paper, 2017). A desmoid tumor (DT) is a benign, locally invasive soft tissue tumor associated with a high recurrence rate but with no metastatic potential. "Therefore, over-expression of miR-21-3p and down-expression of miR-197-3p targeting L1CAM, SERPINA3 and TSPAN3, respectively, could induce or maintain the inflammatory process in mutated desmoid tumor." (PMID 28418912, 2017).
Down and Edwards syndromes (1 paper, 2025). "While these specific serpins have not been directly linked to fetal aneuploidy, other family members, such as SERPINA3 and SERPINA1, have been reported as dysregulated in Down and Edwards syndromes." (PMID 41614738, 2025).
Duchenne muscular dystrophy (1 paper, 2022). Duchenne muscular dystrophy (DMD) is a neuromuscular disease characterized by rapidly progressive muscle weakness and wasting due to degeneration of skeletal, smooth and cardiac muscle. "The previous study identified that spironolactone and lisinopril can downregulate SERPINA3 and treat mice with Duchenne muscular dystrophy, which suggests that SERPINA3 may be related to the salt corticosteroid receptor." (PMID 36712235, 2022).
Fulminant hepatic failure (1 paper, 2020). Hepatic failure refers to the inability of the liver to perform its normal synthetic and metabolic functions, which can result in coagulopathy and alteration in the mental status of a previously healthy individual. "In vivo transdifferentiation of hBMSCs in pigs with fulminant hepatic failure confirmed the similarly upregulated expression of 5 hepatogenic genes (TDO2, HP, SERPINA3, LBP and SAA1), showing a 150-fold change in liver tissues at 7 days after hBMSC transplantation." (PMID 32038110, 2020). "Finally, the five genes (TDO2, HP, SERPINA3, LBP and SAA1) validated in hBMSC transplantation with a fulminant hepatic failure (FHF) model in pigs could be potential biomarkers for the characterization of hBMSC-HLCs." (PMID 32038110, 2020).
haemorrhagic stroke (1 paper, 2008). "The seven gene variants in the six remaining genes – factor XIII, MTHFR, SERPINA3 and glycoproteins Ia, 1b-α, and IIIa – have so far failed to provide evidence to support an increased susceptibility to haemorrhagic stroke." (PMID 19008959, 2008).
HELLP syndrome (1 paper, 2025). A life-threatening condition that can potentially complicate pregnancy. "Combined parent-of-origin analysis of associations between maternal and child SERPINA3 haplotypes and risk of HDPs and severe PE/HELLP syndrome." (PMID 41296456, 2025). "This study analyzed maternal and child polymorphisms and haplotypes in the SERPINA3 gene for associations with HDPs and severe PE/HELLP syndrome." (PMID 41296456, 2025). "The main objective of this study is to investigate the relationship between two SERPINA3 alleles and HDP/PE with severe features (sPE)/HELLP syndrome." (PMID 41296456, 2025).
hemorrhage (1 paper, 2025). Loss of blood from the vascular compartment to the exterior or into nonvascular body space as a result of rupture or severance of the blood vessels. "Higher SERPINA3 levels within 72 hours of hemorrhage onset were independently associated with worse functional recovery (mRS ≥ 3) and increased all-cause mortality at 6 and 12 months." (PMID 40157917, 2025). "Furthermore, we found that plasma SERPINA3 levels within 72 hours were closely associated with hemorrhage volume and clinical manifestations at admission." (PMID 40157917, 2025). "In stratified analyses, SERPINA3 levels were significantly associated with ABC/2, NIHSS, and GCS scores in patients with supratentorial hemorrhage, after adjusting for time from hemorrhage to blood collection, and other potential confounding variables." (PMID 40157917, 2025). "We also examined whether the association between elevated SERPINA3 and worse mRS was independent of NIHSS and hemorrhage volume." (PMID 40157917, 2025).
intracerebral hemorrhage (1 paper, 2025). A cerebrovascular disorder characterized by bleeding into one or both cerebral hemispheres including the basal ganglia and the cerebral cortex. "Despite these limitations, our findings provide strong evidence for the potential value of plasma SERPINA3 as a biomarker for predicting the long-term prognosis of spontaneous intracerebral hemorrhage." (PMID 40157917, 2025). "First, although spatial transcriptomic results indicate increased expression of SERPINA3 in the brain during chronic intracerebral hemorrhage, the exact mechanisms of SERPINA3’s effects on neural function following ICH remain unknown." (PMID 40157917, 2025).
ischemia (1 paper, 2019). A hypoperfusion of the BLOOD through an organ or tissue caused by a PATHOLOGIC CONSTRICTION or obstruction of its BLOOD VESSELS, or an absence of BLOOD CIRCULATION. "In the present study, using a model of AKI to CKD transition in rats, we found that serpinA3 appears in the urine since the first month post-ischemia, when the rats do not even exhibit proteinuria or any sign of glomerular damage." (PMID 31316093, 2019).
kidney cancer (1 paper, 2024). Primary or metastatic malignant neoplasm involving the kidney. "SerpinA3, as well as A2M, alpha-1-acid glycoprotein 2, are considered candidate biomarkers of various cancers, including kidney cancer." (PMID 39896931, 2024).
kidney damage (1 paper, 2025). "Notably, urinary SerpinA3 is virtually undetectable in systemic inflammatory diseases without renal involvement, supporting its specificity as a marker for kidney damage." (PMID 41329353, 2025).
leukaemia (1 paper, 2025). "In leukaemia and lymphoma patients, circulating SERPINA3 was described to be 1.2-fold elevated compared to controls." (PMID 40087712, 2025).
liver inflammation (1 paper, 2024). "Alternatively, a recent study demonstrated the pro-inflammatory effects of SERPINA3 in mice, as hepatocyte-specific Serpina3 knockout was protective against acetaminophen-induced liver inflammation and fibrosis." (PMID 38909263, 2024).
lung adenocarcinoma (1 paper, 2024). A carcinoma that arises from the lung and is characterized by the presence of malignant glandular epithelial cells. "Increased expression of SerpinA3 by tumors was also associated with larger tumor size and poor survival in lung adenocarcinoma patients." (PMID 38279150, 2024).
lung diseases (1 paper, 2020). "Mutations in SERPINA3 have been described to have an impact in lung diseases." (PMID 33072128, 2020).
lupus (1 paper, 2025). "Apolipoprotein E (APOE) and alpha-1-antichymotrypsin (SERPINA3) were both reported to positively correlate with cardiovascular events and lupus activity." (PMID 41614843, 2025).
melanoma in situ (1 paper, 2017). "Strikingly, we found marked increase of SERPINA3 expression in primary invasive melanomas (PM) compared with normal nevi (NN) and melanomas in situ (MIS) (P = 6.8E-5 and 8.4E-4, respectively, Chi-square test)." (PMID 27213583, 2017).
myocarditis (1 paper, 2024). Myocarditis is a condition that is characterized by inflammation of the heart muscle (myocardium). "Furthermore, administration of recombinant SERPINA3 has been observed to exacerbate fibrosis in a Coxsackie-induced myocarditis model." (PMID 38909263, 2024).
Nephroblastoma (1 paper, 2022). An embryonal neoplasm characterized by the presence of epithelial, mesenchymal, and blastema components. "In addition, SERPINA3 has been found in renal tumor cells, such as nephroblastoma, renal carcinoma, and congenital mesodermal nephroma cells." (PMID 36304455, 2022).
neuroblastoma (1 paper, 2021). Neuroblastoma (NB) is the most common solid, extracranial childhood tumor. "We found that polymorphic SERPINA3 I308T (rs142398813) could also prolong toxic oligomeric Aβ 42 triggering neuronal cell death using neuroblastoma SH-SY5Y cell line, thus act as pathogenic chaperon protein." (PMID 33662018, 2021). "Using SH-SY5Y neuroblastoma cell line, we observed until 36 hr preincubated Aβ 42 with SAMP8 type Serpina3 caused neuronal cell death compared to 12 hr preincubated Aβ 42 with SAMR1 or JF1 type Serpina3 proteins." (PMID 33662018, 2021).
pancreatitis (1 paper, 2023). Inflammation of the pancreas. "SERPINA3 may be an effective inhibitor of pancreatitis-induced lung injury." (PMID 37197655, 2023).